MPO (myeloperoxidase)
Diseases named in the same sentence as MPO in open-access papers (continued):
Sharing a sentence is not in itself a finding about the gene and the disease.
Sepsis (continued). "In a population of patients with trauma-induced inflammation, the study found that MPO levels in patients with sepsis were significantly higher compared to those without sepsis." (PMID 36147548, 2022). "Similar results were shown in models of acute lung injury after sepsis (decreased TNF-α, IL-1β, and IL-6 secretion) and paraformaldehyde injury (decreased cell death, MyeloPeroxidase activity, parenchymal vascular permeability, TNF-α and IL-6 secretion, and increased IL-10 secretion)." (PMID 35874678, 2022). "For this, using a well-designed cecal ligation and puncture (CLP)-induced sepsis mouse model, we comparatively measured the level and cost-effectiveness of sepsis biomarkers such as DNI, myeloperoxidase (MPO), procalcitonin (PCT), and tumor necrosis factor-alpha (TNF-α)." (PMID 35334545, 2022). "Here, our results have shown that in CLP or LPS-injected mice, CA attenuated sepsis-induced structural damage and inflammatory cell infiltration in lung tissue and reduced lung wet/dry ratio and inflammatory cell infiltration in BALF and MPO activity." (PMID 34737695, 2021). "The results of this study showed a significant increase of the oxidative damage indexes (MPO, MDA, and SOD) in mice with gut-origin sepsis, while lentinan could reduce the oxidative damage." (PMID 34790828, 2021). "Additionally, we investigated a new mechanism of neutrophil-derived myeloperoxidase (MPO) damage to glycocalyx of vascular endothelial cells, which is different from previous findings in sepsis." (PMID 34646891, 2021). "Clopidogrel treatment led to similar increase in MPO concentration, indicating that clopidogrel treatment did not modify systemic neutrophil activation during sepsis and septic shock." (PMID 34447900, 2021). "The activity of MPO, the levels of pro-inflammatory cytokines, including TNF-α and IL-6, in the intestine, the activity of DAO and the content of MDA in the serum in the sham, sepsis and sesamin (50 μM) + sepsis groups were examined." (PMID 32893702, 2020). "Moreover, DEX markedly attenuated sepsis-induced lung inflammation, as evidenced by the decrease in the number of PMNs in the BALF, lung MPO activity and proinflammatory cytokines in the BALF." (PMID 31927655, 2020). "The CLP-induced sepsis model established in this study demonstrated significantly increased levels of cTnI, NT-proBNP and Mb in sera and a high level of MPO in heart tissue, indicating that the heart tissue and cells were seriously damaged as a result of the CLP-induced sepsis." (PMID 32423469, 2020). "Moreover, MRS treatment decreased the expression of MPO and MDA, and increased the levels of GSH and SOD, thereby reducing oxidative stress injury during sepsis." (PMID 30779706, 2019). "A relevant role of neutrophils can be excluded, first, because of limited expression of CX43 in response to sepsis and because no alterations of myeloperoxidase activity in the liver of mice 10 hr after CLP was observed in response to CX43 blockade." (PMID 30735126, 2019). "Moreover, significant lower levels of TNF-α, IL-6, bacterial loads, MPO, and ROS were discovered in the KO-CLP sepsis group in contrast to the WT-CLP sepsis group." (PMID 28694565, 2017). "We found significantly higher levels of myeloperoxidase in patients with sepsis and septic shock compared to patients without sepsis (60 ng/ml versus 43 ng/ml, P = 0.002)." (PMID 28916973, 2017). "The MPO levels in patients with sepsis were significantly higher compared with patients without sepsis (60 ng/mL [IQR 36–88 ng/mL] versus 43 ng/mL [IQR 23–75 ng/mL], P = 0.002)." (PMID 28916973, 2017). "We conducted a prospective study in a cohort of SIRS patients in the ICU to determine the discriminative value of MPO between non-infective SIRS and sepsis and the prognostic value of MPO as a biomarker for mortality." (PMID 28916973, 2017).
Sepsis (continued). "CRP and MPO distinguished sepsis from non-infectious SIRS similarly (MPO: AUC 0.603 [95% confidence interval (CI) 0.538–0.668] versus CRP: AUC 0.636 [CI 0.572–0.700])." (PMID 28916973, 2017). "Multiple studies support this finding, indicating that non-survivors or those with more severe sepsis experience increased levels of neutrophil induced tissue damage and MPO generation." (PMID 26468651, 2015). "It is assumed but not proven that the plasma mediators may lead to the buildup of MPO as well as ROS and RNS levels in various organs which eventually fail in sepsis." (PMID 23208733, 2012). "Not surprisingly, a normal MPO content was observed in only 2% of neutrophils from patients with severe sepsis." (PMID 22761804, 2012). "Furthermore, we found that myeloperoxidase can effectively predict short-term mortality among sepsis patients, regardless of their DIC status." (PMID 41476244, 2025). "Furthermore, animal models of lung injury have shown that FOXM1 is essential in regulating neutrophil response and secretion of MPO and cathepsin G, both of which were enriched in neonates that did not survive sepsis." (PMID 40655143, 2025). "This network uncovered regulatory interactions among genes like MPO, CXCR2, ITGAM, SPI1, SPI1 and EP300, suggesting these TFs may participate in sepsis-related immune responses and inflammatory regulation by modulating the transcriptional activity of core genes." (PMID 41259376, 2025). "While studies specifically linking NO levels to NETosis in human sepsis remain limited, combining NO biomarkers with NET-related markers—such as cell-free DNA and MPO-DNA complexes—could enhance prognostic stratification by integrating information on vascular, immune, and coagulative dysfunction." (PMID 40806591, 2025). "We detected the expression level of Acod1 mRNA in peripheral blood neutrophils of healthy volunteers and sepsis patients, and determined the concentration of pro‐inflammatory factor TNF‐α in peripheral blood, as well as the content of NETs' characteristic components CitH3‐DNA and MPO‐DNA." (PMID 40586264, 2025). "Additionally, we analyzed the predictive efficacy of these predictors and found that the combination of MPO and HOCl with TNF-α, WBC, and APACHE II score could better predict the occurrence of NOAF in sepsis." (PMID 39030470, 2024). "Similarly, our study found that MPO-DNA levels were significantly higher in sepsis patients compared to non-sepsis patients and healthy controls." (PMID 39457503, 2024). "Similarly, Spearman correlation analysis showed that MPO-DNA and cf-DNA levels were positively correlated with PCT and SOFA scores to varying degrees, suggesting that abnormal NET formation plays an important role in the progression of sepsis." (PMID 39457503, 2024). "To explore the effects of FTB on NET levels in the peripheral blood of rats with sepsis, we first extracted neutrophils from the peripheral blood of rats in each group, induced NET production with PMA, and stained the cells with immunofluorescent anti-MPO, anti-H3-Cit, and SYTOX Green." (PMID 36408247, 2022). "The median myeloperoxidase index was found to be higher in sepsis versus non-infectious SIRS." (PMID 36147548, 2022). "Treatment with montelukast, a CysLT1 receptor antagonist, was previously shown to prevent the rise of MPO activity, GSH depletion, and lipid peroxidation in the liver of septic rats, suggesting that neutrophilic infiltration into tissues is a major contributor to sepsis-induced oxidative stress." (PMID 36359365, 2022). "However, few downregulated proteins in sepsis patients compared to HC were AHSG, and PROS1, whereas compared to w/o sepsis, patients were AHSG, PROS1, DEFA1, SERPINA3, MPO, and MMRN1 (Azurophil granule, azurophil granule lumen and secretory granule lumen (GO:0042582, GO:0035578 and GO:0034774))." (PMID 35681439, 2022).
Sepsis (continued). "In addition, the immunofluorescence analysis of inflammatory lesions in mice with LPS-induced sepsis showed that both MPO and CitH3 were more strongly expressed in the LPS-only group, whereas the LPS + LPC group exhibited reduced expression of both MPO and CitH3." (PMID 35859904, 2022). "Twenty-four hours after sepsis, lung injury was assayed by lung histology, the ratio of polymorphonuclear leukocytes (PMNs) to total cells in the bronchoalveolar lavage fluid (BALF), myeloperoxidase (MPO) activity, BALF protein content and the lung wet-to-dry (W/D) weight ratio." (PMID 31927655, 2020). "Serum samples of sepsis patients (as compared to non-septic patients) contained higher neutrophil counts (13.3 × 109 vs. 6.5 × 109 cells/l) and higher concentrations of MPO (13.1 vs. 8.8 ng protein/mL), IL-6 (188 vs. 23 pg/mL), and TNFα (348 vs. 63 pg/mL)." (PMID 32050431, 2020). "However, the activity of MPO in the intestines and livers of the rats in the sepsis+MLD group revealed no evident changes, compared with the sepsis groups (p > 0.05)." (PMID 33145344, 2020). "Furthermore, there was a positive correlation between cfDNA and neutrophil-derived MPO, an enzyme released during NETosis in sepsis patients but not in trauma patients." (PMID 31119471, 2019). "The aim of this study was to compare the plasma levels of MPO-DNA and cf-DNA between septic shock patients and healthy volunteers, as well as to investigate the relationship of circulating NET levels with 28-day mortality, organ dysfunction, and known parameters of the severity of sepsis." (PMID 30005596, 2018). "Using low-grade and midgrade models of sepsis in rats, this study found that the AChE and CAT activities in the diaphragm decreased, while the contents of TBARS and protein carbonyls, the activity of MPO and SOD, and the SOD/CAT ratios increased at 24 h after CLP surgery." (PMID 29230271, 2017). "In non-running mice, sepsis elevated pulmonary MPO compared to control." (PMID 28789683, 2017). "Moreover, sepsis-induced high bacteremia and an intense systemic inflammatory response characterized by elevated serum concentrations of TNF-α, CK-MB, BUN and AST and increased neutrophil accumulation in the lungs, indicated by increased MPO activity." (PMID 26849138, 2016). "MPO activity in the heart of caPI3K mice was not significantly elevated in response to sepsis and it was significantly lower than the MPO levels in the WT CLP myocardium, indicating that expression of the p110α transgene prevented neutrophil accumulation in the heart." (PMID 23028587, 2012). "However, the development of pulmonary edema or MPO activity in the lungs was not alleviated by sympathetic blockade in this phase of sepsis." (PMID 19580652, 2009). "However, the potential of MPO and HOCl as predictors of NOAF in sepsis remains unclear." (PMID 39030470, 2024). "Therefore, DEFA4, ELANE, MPO, and TFRC might be related to immune paralysis in sepsis." (PMID 36532037, 2022). "However, as sepsis at 7 h does not increase MPO in the heart, we speculate that protection by exercise may not have manifested in the heart in contrast to protection in immunogenic organs where neutrophils become abundant (i.e., lung and liver)." (PMID 28789683, 2017). "Therefore, we hypothesized that myeloperoxidase can differentiate between sepsis and non-infectious SIRS in patients with systemic inflammatory response syndrome in the intensive care unit (ICU)." (PMID 28916973, 2017). "Therefore, MPO could be a diagnostic biomarker differentiating between SIRS without infection and sepsis." (PMID 28916973, 2017). "In this model of sepsis, P2Y1 blockade did not improve activity of MPO in lungs and kidneys nor altered platelet interaction with other cells." (PMID 36405709, 2022). "In a nonhuman primate model of E.coli-induced sepsis, pretreatment with APC abrogated release of MPO from neutrophils, an enzyme essential for NETosis." (PMID 34712384, 2021).
Sepsis (continued). "The MPO-DNA level was inversely correlated with both the MAP and the P/F ratio on days 3 and 7 in the patients with sepsis, whereas the cf-DNA level was not correlated with either parameter." (PMID 30005596, 2018). "Prior to our study, a limited amount of studies investigated the discriminative value of MPO between non-infectious SIRS and sepsis." (PMID 28916973, 2017). "We show that MPO had a similar discriminative value to CRP and that leukocytes did not differentiate between non-infectious SIRS and sepsis." (PMID 28916973, 2017). "We compared the discriminative value between sepsis and non-infectious SIRS of MPO with CRP and leukocytes." (PMID 28916973, 2017). "In summary, our investigation conducted comprehensive bioinformatics analysis on two gene datasets (GSE28750 and GSE74224) and discerned LTF, LCN2, ELANE, MPO and CEACAM8 as key up-regulated genes in sepsis patients when compared with non-sepsis critically ill controls." (PMID 38912048, 2024). "Thus, as sepsis biomarkers, HBP and MPO were not as prone as IL-6 and IL-8 to the effect of sample timing." (PMID 33461369, 2021). "In our patient cohort, MPO could differentiate between SIRS without infection and sepsis." (PMID 28916973, 2017).
COVID-19 (239 papers, 2020 to 2026). A disease caused by infection with severe acute respiratory syndrome coronavirus 2. "Cell-free DNA and myeloperoxidase (MPO)-DNA correlate with the number of neutrophils; so, in the COVID-19 inflammation that predisposes to DVT, they appear increased." (PMID 40861621, 2025). "Another study indicates that increased neutrophil MPO activation and endothelial glycocalyx damage are independently associated with COVID-19 severity." (PMID 40241896, 2025). "In COVID-19, the serial monitoring of plasma MPO-DNA and CitH3 levels aids in identifying high-risk patients progressing to ARDS or thrombosis." (PMID 41156629, 2025). "While certain MPO polymorphisms have been tied to inflammatory or vascular conditions, their relevance to COVID-19 remains unexplored." (PMID 41209585, 2025). "MPO has been implicated in many diseases, including CVDs, renal diseases, lung diseases (including COVID-19), neurodegenerative diseases, and cancers." (PMID 38275657, 2024). "Further supporting the similarity between bacterial sepsis and COVID-19-induced viral sepsis, we observed an elevation of factors associated with oxidative stress (e.g., MPO) and factors released from damaged (organ) tissue (NGAL, Cystatin C, myoglobin)." (PMID 36851312, 2023). "In the COVID-19 patients, we measured two representative markers of NETs, circulating nucleosomes and MPO-DNA, and both were closely associated." (PMID 37051234, 2023). "Treatment with platelet releasate from COVID-19 patients caused healthy neutrophils to produce more MPO-DNA complexes." (PMID 36999030, 2023). "In severe COVID-19, increased MPO activity causes soluble endothelial glycocalyx (EG) shedding and its inhibition protects against EG degradation." (PMID 37569455, 2023). "The increased levels of CitH3 and MPO, which are associated with NETs, further support the involvement of NETs in the pathogenesis of COVID-19 related ARDS." (PMID 38283037, 2023). "Cell-free DNA and MPO/DNA complexes were higher in plasma of patients with COVID-19 than in healthy controls and were associated with severity of COVID-19." (PMID 33982161, 2022). "Circulating leukocyte count, IL-6, and myeloperoxidase levels were positively correlated with MMP-9 concentration in patients with COVID-19, which suggests that MMP-9 is associated with inflammation in patients with COVID-19." (PMID 36142454, 2022). "The enhanced MPO associated with these conditions further predisposes affected individuals towards both severe complications of COVID-19, other pathological conditions, and biochemical imbalances such as depletion of critical species, e.g., NO." (PMID 33390833, 2021). "E-cigarette users' sputum had increased NET-related proteins, such as myeloperoxidase, azurocidin, and protein-arginine deiminase 4, suggesting an association of vaping and organ damage in COVID-19." (PMID 34055688, 2021). "In this regard, COVID-19-associated thrombosis presents higher plasma levels of NETs biomarkers, such as cfDNA, citH3, and MPO-DNA, and NETs structures have also been identified in arteriolar microthrombi." (PMID 35052711, 2021). "A profusion of ImNs in COVID-19 BAL was associated with massive production of myeloperoxidase (MPO) and neutrophil elastase (ELA), two antimicrobial and cytotoxic proteins known to be highly concentrated in the azurophilic granule of ImN." (PMID 34616409, 2021). "As COVID-19 is associated with pulmonary and vascular manifestations, we also investigated autoantibodies targeting myeloperoxidase (MPO), proteinase 3 (PR3) and glomerular basement membrane (GBM)." (PMID 33263103, 2020). "In this context, it should be emphasized that elevated levels of myeloperoxidase (MPO)–DNA complexes are associated with the need for ventilation in COVID-19 patients." (PMID 33291455, 2020).